SCG2 (secretogranin II)
Description:
Neuroendocrine protein of the granin family that regulates the biogenesis of secretory granules.
Synonyms: SgII; SN; CHGC; EM66
Tractability: Antibody: UniProt places it where antibodies can reach, with medium confidence; UniProt predicts a signal peptide or a membrane-spanning region; its Gene Ontology location is reachable by antibodies, with medium confidence. PROTAC: its protein half-life has been measured.
Gene: Protein-coding gene on chromosome 2 (223,596,940 to 223,602,361, reverse strand). Ensembl gene ENSG00000171951.
Subcellular location: Secreted
Subcellular location (Human Protein Atlas): Golgi apparatus; Vesicles; Predicted to be secreted
Pathways (Reactome):
Metabolism of proteins: Post-translational protein phosphorylation; Regulation of Insulin-like Growth Factor (IGF) transport and uptake by Insulin-like Growth Factor Binding Proteins (IGFBPs)
Gene Ontology:
Molecular function: chemoattractant activity; cytokine activity; protein binding
Biological process: angiogenesis; eosinophil chemotaxis; induction of positive chemotaxis; intracellular signal transduction; MAPK cascade; negative regulation of endothelial cell apoptotic process; negative regulation of extrinsic apoptotic signaling pathway; positive chemotaxis; positive regulation of endothelial cell proliferation; endothelial cell migration; inflammatory response; negative regulation of endothelial cell proliferation; protein secretion
Cellular component: extracellular region; endoplasmic reticulum lumen; secretory granule; dense core granule; neuronal dense core vesicle
Genetic constraint (gnomAD): Loss-of-function variants: 23 observed, 51.26 expected, observed/expected ratio (o/e) 0.45, 90% interval 0.32 to 0.64. The upper end of that interval is the gene's LOEUF score, 0.64, which puts it in group 2 of 6, group 1 being the genes least tolerant of losing a copy. Missense variants: 730 observed, 767.8 expected, observed/expected ratio (o/e) 0.95, 90% interval 0.89 to 1.01. Synonymous variants: 288 observed, 275.33 expected, observed/expected ratio (o/e) 1.05, 90% interval 0.95 to 1.15.
Homologues: Orthologues: macaque SCG2 (98% identical), chimpanzee SCG2 (94% identical), dog SCG2 (89% identical), pig SCG2 (89% identical), rabbit SCG2 (88% identical), mouse Scg2 (82% identical), rat Scg2 (81% identical), guinea pig SCG2 (75% identical), tropical clawed frog scg2 (48% identical), zebrafish scg2b (25% identical).
Diseases named in the same sentence as SCG2 in open-access papers:
SCG2 is named in the same sentence as 67 diseases in open-access papers, as found by Europe PMC text mining. Sharing a sentence is not in itself a finding about the gene and the disease. The quoted sentences say what the papers report.
colorectal cancer (7 papers, 2021 to 2025). A primary or metastatic malignant neoplasm that affects the colon or rectum. "SCG2 is an independent prognostic factor in colorectal cancer, which is associated with macrophage polarization and immune infiltration." (PMID 36419120, 2022). "In colorectal cancer (CRC), a study has identified that SCG2 is linked to the infiltration of tumor immune cells, promotes M2 macrophage polarization, and correlates with the expression of immune checkpoints in CRC." (PMID 39995998, 2025). "SCG2 has been increasingly demonstrated to be highly expressed in colorectal carcinoma, renal carcinoma, melanoma, as well as other cancers." (PMID 39995998, 2025). "Recent studies have demonstrated the impact of SCG2 on the clinical stage, and the influence of macrophage polarization on immunotherapy in colorectal cancer." (PMID 36675186, 2023). "It was found that SCG2 can predict prognosis in breast cancer, nonsmall cell lung cancer, and colorectal cancer." (PMID 36467500, 2022). "In the present study, we explored the role of SCG2 in colorectal cancer, revealed its prognostic value, biological functions, associated pathways, and regulation of tumor immunity by analyzing open-access databases comprehensively." (PMID 35047505, 2021). "There may be a link between SCG2 and APC in the development of colorectal cancer, making SCG2 play an essential role in disease progression." (PMID 35844556, 2022).
breast carcinoma (6 papers, 2020 to 2023). "SCG2 has been identified as a prognostic biomarker associated with immune infiltration in CRC, bladder cancer, breast cancer, and lung adenocarcinoma." (PMID 36910014, 2023). "For the first time, the current study reported that SCG2 had a higher expression level and acted as an unfavorable prognostic marker in breast cancer." (PMID 35602610, 2022). "As expected, seven of the TME prognostic genes (NOS2, SCG2, RGS3, EMP1, PDLIM4, PCDH9, and GFI1) showed dual functions in breast cancer progression." (PMID 36936167, 2023). "To further understand the biology of NE breast tumors, we used Molecular Taxonomy of Breast Cancer International Consortium (METABRIC) database and isolated tumors which expressed neuroendocrine markers SCG2, CHGB, CHGA and SYP." (PMID 37071013, 2023). "TNFSF12, TNNI3, SCG2, and COL4A3 were identified as prognostic biomarkers in breast cancer by univariate and multivariate Cox regression algorithms." (PMID 35602610, 2022). "The roles of other IRGs in our signature in breast cancer, including IGHE, SCG2, NPR3 and FABP6, require further clarification." (PMID 33216733, 2020). "Seven of the 15 TME prognostic genes (NOS2, SCG2, RGS3, EMP1, PDLIM4, PCDH9, and GFI1) were involved in enhancing cell proliferation, destroying cell apoptosis, promoting cell invasion, or migration in breast cancer." (PMID 36936167, 2023). "Surprisingly, we also observed the unexpected appearance of ramifications reminiscent of neuroendocrine cells and an increased expression of neuroendocrine markers SCG2 and CHGB in these cells, indicating that SASP is able to induce NED in breast cancer epithelial cells." (PMID 37071013, 2023). "However, the detailed function of SCG2 in breast cancer has not been well-defined." (PMID 35602610, 2022).
melanoma (6 papers, 2014 to 2025). A malignant, usually aggressive tumor composed of atypical, neoplastic melanocytes. "SCG2 (secretogranin 2) is downregulated by both free tris DBA and Tris DBA HANP, and low expression of SCG2 is associated with improved prognosis in human melanoma." (PMID 30824801, 2019). "Loss of desmoglein 2 increases expression of secretogranin II, followed by an enhanced migratory activity of melanoma cells." (PMID 24558503, 2014). "By conducting transcriptional analysis between SCG2-overexpressing (OE) and control melanoma cells, we detected a downregulation of components of the antigen presenting machinery (APM), which is important for the assembly of the MHC class I complex." (PMID 36906639, 2023). "Correlating expression levels in tissue samples of primary melanoma and metastases revealed that secretogranin 2 (SCG2) is highly expressed in advanced melanoma patients with poor overall survival (OS) rates." (PMID 36906639, 2023). "For example, Secretogranin II (SCG2) was overexpressed in melanoma tissues obtained from patients with a poor prognosis, and promoted immune escape by downregulating the expression of MHC-I ((major histocompatibility complex I))." (PMID 37174106, 2023). "Dsg2 depletion also increases the expression of migration-related genes such as secretogranin II, which enhanced the migratory activity of melanoma cells." (PMID 34168237, 2021). "The bioactive peptide derived from secretogranin II, secretoneurin, is known to exert chemoattractive functions and was demonstrated here to stimulate melanoma cell migration." (PMID 24558503, 2014). "Our data add a new pathway of regulating melanoma cell migration related to a desmoglein 2 – secretogranin II axis." (PMID 24558503, 2014). "Strongest overexpression was found for secretogranin II which has not been reported in melanoma cells before." (PMID 24558503, 2014).
calcific aortic valve disease (4 papers, 2021 to 2024). "Moreover, increased levels of Scg2 have been associated with favorable clinical outcomes in certain cancers, such as kidney renal clear cell carcinoma, and in calcific aortic valve disease (CAVD) patients." (PMID 39518908, 2024). "Moreover, in the present study, we investigated the effect of angiogenesis-related factors on aortic valve calcification and discovered that SCG2 and ZEB1 may be the key aortic valve calcification factors." (PMID 36824454, 2023). "SCG2 and ZEB1 are significant influencing factors for aortic valve calcification, providing novel ideas for the diagnosis and treatment of CAVD patients." (PMID 36824454, 2023). "Single-cell sequencing analysis and immunohistochemical staining of human aortic valve tissue samples showed that SCG2 and CCL19 were increased in Calcific aortic valve disease (CAVD) valves." (PMID 36589450, 2022). "The expression of SPP1, TNC, SCG2, FAM20A, and CD52 was all significantly up-regulated in calcific aortic valve disease." (PMID 34020624, 2021).
neuroblastoma (4 papers, 2017 to 2021). Neuroblastoma (NB) is the most common solid, extracranial childhood tumor. "Secretogranin II, as a key AP‐1‐regulated protein, mediates neuronal differentiation and protects neuroblastoma cells from nitric oxide‐induced apoptosis." (PMID 34160138, 2021). "Already 72 h after transfection, the neuroblastoma cells experienced a marked increase of expression levels of the differentiation markers SCG2 and NPY at mRNA levels." (PMID 33659885, 2021). "Secretogranin II (SCG2), a key AP‐1‐regulated member of the granin family, is a neuroendocrine protein that regulates the biogenesis of secretory granules involved in hormonal peptide sorting, mediates neuronal differentiation, and protects neuroblastoma cells from nitric oxide‐induced apoptosis." (PMID 34160138, 2021).
bladder cancer (3 papers, 2021 to 2025). "MRNA expression levels of COL5A2 and SCG2 were considerably elevated in the bladder cancer cell strains (T24 and SW1710) relative to standard bladder epithelial cell strain (SV-HUC-1)." (PMID 39995998, 2025). "Compared with the normal bladder epithelial cell line (SV-HUC-1), the expression levels of 2 model genes (COL5A2 and SCG2) in bladder cancer cell lines (T24 and SW1710) were significantly elevated." (PMID 39995998, 2025). "Secretogranin II (SCG2) is a member of the chromogranin family of acidic secretory proteins, has a role in tumor microenvironment (TME) of lung adenocarcinoma and bladder cancer." (PMID 35047505, 2021). "Besides, SCG2 could predict prognosis in Non-small cell lung cancer as a potentially secreted biomarker, reflect the TME of lung adenocarcinoma and bladder cancer." (PMID 35047505, 2021).
Hypertension (3 papers, 2020 to 2023). The presence of chronic increased pressure in the systemic arterial system. "Scg2 (Secretogranin II) is a precursor of various neuropeptides, such as secretoneurin, and a genetic polymorphism in African-American subjects has been associated with hypertension." (PMID 37660920, 2023). "SCG2 may be a biomarker of bipolar disease and is known to regulate hypertension in humans, perhaps explaining the poorer survival outcomes observed here following upregulation of this gene." (PMID 32756008, 2020).
multiple sclerosis (3 papers, 2016 to 2021). A progressive autoimmune disorder affecting the central nervous system resulting in demyelination. "Previously, SCG2 has been suggested as a CSF biomarker for multiple sclerosis, and mild cognitive impairment, pre-stage Alzheimer’s disease." (PMID 34815513, 2021). "A previous study using mass spectrometry showed that the concentration of SCG2 decreased in the CSF of patients with multiple sclerosis, and on the contrary, increased in those with mild cognitive impairment, a pre-stage Alzheimer’s disease." (PMID 34815513, 2021). "Consistent with our findings, reduced levels of CSF SCG2 in AD and multiple sclerosis (MS) have been reported." (PMID 32552841, 2020). "SCG3 and SCG2 were previously evaluated as potential biomarkers of multiple sclerosis and decreased levels were observed for SCG3 and SCG2 in serum and CSF samples of multiple sclerosis patients." (PMID 27186164, 2016).
neuroendocrine tumors (3 papers, 2011 to 2021). "Studies have revealed that the derived peptides of SCG2, such as secretoneurin (SN) and EM66, are useful markers of neuroendocrine tumors." (PMID 35047505, 2021).
Cognitive impairment (2 papers, 2021 to 2023). Abnormal cognition is characterized by deficits in thinking, reasoning, or remembering. "Proteins that could distinguish cognitive impairment were mainly neuronal proteins (VGF, NPTX2, NPTXR, and SCG2)." (PMID 37160957, 2023).
diabetes (2 papers, 2021 to 2023). "Secretogranin II, has anti‐inflammatory properties and participates in inflammatory reaction, involves in the pathogenesis of diabetes." (PMID 37249284, 2023). "In addition, CHGA, CHGB, SCG2, and some CHGA cleavage products affect glucose homeostasis and different types of diabetes." (PMID 37249284, 2023).
lung cancer (2 papers, 2019 to 2022). A malignant neoplasm involving the lung. "The prognostic value related to the worse prognosis of IL-8, SCG2, NCAM1, CNTN1, CADM1, NPTX1, and APOD tumor transcripts were evaluated in seven lung cancer transcriptome datasets (validation set)." (PMID 31455042, 2019).
meningioma (2 papers, 2018 to 2026). A generally slow growing tumor attached to the dura mater. "RUNDC3B, SCG2, SLC1A3, EXT1 (as well as RHOBTB3, TSPAN7, CAV2, MLPH) were part of the NF2/SMARCB1 expression subclass of a recent study on genomic profiling of meningioma." (PMID 29662628, 2018). "Six of these genes were usually underexpressed (RUNDC3B, ANGPT2, PHLDA2, CAV2, EDNRA, and SCG2) in non-aggressive/non-recurrent tumors and overexpressed in more aggressive/recurrent meningiomas." (PMID 29662628, 2018).
prostate carcinoma (2 papers, 2017 to 2019). A carcinoma that arises from epithelial cells of the prostate gland. "SCG2 was a member of the chromogranin/secretogranin family of neuroendocrine secretory proteins, and it might contribute to the neuroendocrine differentiation by promoting the formation of secretory granules and the proliferation of prostate cancer cells." (PMID 28796930, 2017). "Although there were no studies to discuss the roles of SCG5 in cancer, its family members secretogranin II and III have been seen to be overexpressed in prostate cancer and small cell lung carcinoma, suggesting SCG5 may also be oncogenic for LSCC." (PMID 31565549, 2019).
prostate small cell carcinoma (2 papers, 2019 to 2020). A neuroendocrine carcinoma of the prostate gland with unfavorable prognosis, composed of small cells containing neurosecretory granules. "SCG2 encodes for secretogranin, among the NE markers identified in prostate small cell carcinomas by a molecular characterization study that highlighted a diverse repertoire of genes reflecting characteristics of their NE cell of origin." (PMID 32041153, 2020). "Scg2 is a secreted neuroendocrine marker observed in prostatic small-cell neuroendocrine carcinoma." (PMID 31248178, 2019).
Stroke (2 papers, 2018 to 2025). Sudden impairment of blood flow to a part of the brain due to occlusion or rupture of an artery to the brain. "Scg2 expression is spontaneously induced after stroke over time and further enhanced by rehabilitation, suggesting that rehabilitation-induced rewiring builds upon spontaneous rewiring." (PMID 40191711, 2025). "In terms of the molecular mechanisms, exercise induces BDNF and Scg2 expression in the brain and spinal cord and could support the induction of rewiring and recovery after stroke." (PMID 40191711, 2025). "Expression of SCG2 is modulated by extracellular calcium, and it can induce expression of the anti-apoptotic protein Bcl2 through activation of JAK2/STAT3 signaling, providing protection in a murine stroke model." (PMID 30670947, 2018).
asthma (1 paper, 2018). "It has also been reported that secretogranin II (known as chromogranin C), is a potent chemoattractant for eosinophils, which play a critical role in asthma." (PMID 30081920, 2018).
Autoimmunity (1 paper, 2024). The occurrence of an immune reaction against the organism's own cells or tissues. "Future studies should aim to validate these findings across different models and further investigate the functional roles of Ffar1 and Scg2 in human CNS inflammation and autoimmunity." (PMID 39518908, 2024).
breast tumors (1 paper, 2022). "We isolated human breast tumors that displayed NED based on their co‐expression of four NED markers SCG2, CHGB, CHGA, and synaptophysin, SYP." (PMID 35653631, 2022).
Cachexia (1 paper, 2019). Severe weight loss, wasting of muscle, loss of appetite, and general debility related to a chronic disease. "Based on the fact that circulating levels of tumor-derived factors were correlated with cachexia development and predicted outcome in cancer, we also investigated the predictive potential of seven transcripts (NCAM1, CNTN1, SCG2, CADM1, IL-8, NPTX1, and APOD)." (PMID 31455042, 2019).
colon adenocarcinoma (1 paper, 2021). "However, SCG2 expression was significantly lower in colon adenocarcinoma (COAD), kidney chromophobe (KICH), prostate adenocarcinoma (PRAD), rectum adenocarcinoma (READ), stomach adenocarcinoma (STAD), uterine corpus endometrial carcinoma (UCEC) compared with adjacent normal tissues." (PMID 35047505, 2021).
congenital adrenal hyperplasia (1 paper, 2022). Congenital adrenal hyperplasia (CAH) is an inherited endocrine disorder caused by a steroidogenic enzyme deficiency that is characterized by adrenal insufficiency and variable degrees of hyper or hypo androgyny manifestations, depending of the type and the severity of the disease. "Upregulation of genes associated with other diseases, renal dysfunction or cancer was also observed, such as Fras1 (Fraser syndrome 1), Cyp21a1 (congenital adrenal hyperplasia), Dbh (associated with kidney dysfunction), and Akr1c1/Myt1/Myf6/Scg2 (kidney cancer)." (PMID 36130284, 2022).
developmental delay (1 paper, 2021). "With only 5 μL clinical serum samples, the E-NPIS revealed the increase in SCG2 concentration in patients with developmental delay." (PMID 34815513, 2021). "Whole serum samples (5 μL) of eight patients with developmental delay and five controls were 1:10 diluted in a buffer for measurement of SCG2 using the E-NPIS." (PMID 34815513, 2021). "The analysis using the nanoplasmonic immunosensor revealed higher serum SCG2 levels in pediatric patients with developmental delay than in the control group." (PMID 34815513, 2021). "In our study, the patients with developmental delay showed an increase in the serum level of SCG2 as compared with the control group." (PMID 34815513, 2021). "The levels of SCG2 were higher in the developmental delay group than in the control group, although the difference was not statistically significant (p = 0.089)." (PMID 34815513, 2021). "In conclusion, this highly sensitive nanoplasmonic immunosensor enabled the detection of SCG2 in small volumes of serum, and revealed the higher serum SCG2 levels in patients with developmental delay." (PMID 34815513, 2021). "Interestingly, SCG2 expression reduced in the brain tissue of an animal model of developmental delay that showed attenuated synaptic plasticity and aberrant neurogenesis." (PMID 34815513, 2021). "We then examined SCG2 expression in a PTPRT−/− null mouse model of developmental delay." (PMID 34815513, 2021). "In conclusion, we developed a highly sensitive nanoplasmonic immunosensor for the detection of serum SCG2, which could be used for the early diagnosis of neurodevelopmental disorders such as global developmental delay." (PMID 34815513, 2021).
glioma (1 paper, 2022). A benign or malignant brain and spinal cord tumor that arises from glial cells (astrocytes, oligodendrocytes, ependymal cells). "Other SHH-1A associated genes were the neuroendocrine-specific tumor genes SST and SCG2; ARPP21, encoding an RNA-binding protein found in glioma, and SOX6, a tumor marker expressed by not fully differentiated neuronal and glial cells." (PMID 35501487, 2022).